MGMT (O-6-methylguanine-DNA methyltransferase)
Diseases named in the same sentence as MGMT in open-access papers (continued):
Sharing a sentence is not in itself a finding about the gene and the disease.
cancer (continued). "Notably, in TMZ-resistant LN229 cells, metformin suppressed key proteins, including mitochondrial transcription factor A, Twist, and O-6-methylguanine-DNA methyltransferase (MGMT), which are associated with drug resistance and cancer cell survival." (PMID 39944825, 2025). "Substantial responses to temozolomide suggest that this drug represents an effective treatment for patients with MGMT deficiency, regardless of cancer type." (PMID 40458731, 2025). "The cancer forms were selected on the basis of high fractions of tumors with MGMT methylation." (PMID 39980037, 2025). "Significant progress has been made in understanding the function of MGMT, yet several avenues remain to be explored that could shape the next generation of cancer therapies." (PMID 40895460, 2025). "Additionally, MGMT promoter methylation was investigated, with findings indicating significant methylation in carcinomas." (PMID 39859246, 2025). "The activity of MGMT is, therefore, a critical factor in the cell response to alkylating chemotherapy, as it can influence the effectiveness of the treatment and the survival of the cancer cells." (PMID 39055560, 2024). "MGMT encodes for an enzyme involved in DNA repair and protects cells from mutations; however, methylation of the MGMT promoter results in a decrease in MGMT expression, which results in a reduction in overall DNA repair, enabling cancer cells to become sensitive to chemotherapy." (PMID 39594997, 2024). "The current study served as a follow-up to the previously published effort where the viability profile of GB cell lines U-251 MG (weakly MGMT-positive) and T98-G (strongly MGMT-positive) was established following inhibition of various pathways putatively crucial for the survival of the cancer cells." (PMID 38383756, 2024). "This article aims to provide a comprehensive exploration of the multifaceted role of MGMT in the context of cancer therapy, examining its critical function in DNA repair, its impact on the effectiveness of alkylating chemotherapeutic agents, and its potential modulation of the outcomes of radiation." (PMID 39055560, 2024). "As the body of research in this area expands, the unraveling of MGMT’s complexities may herald a new era of targeted and efficacious cancer treatments, offering hope for improved patient outcomes." (PMID 39055560, 2024). "Knocking out MGMT inhibits cancer cell growth in vitro and in vivo." (PMID 39041891, 2024). "The activity of MGMT is particularly significant in cancer treatment." (PMID 38672496, 2024). "Second, it delves into the development of cancer therapeutic strategies that target MGMT." (PMID 38254819, 2024). "Of note, MGMT was the first cancer DNA methylation biomarker to be discovered." (PMID 39056791, 2024). "Exosomal-derived mRNA has also been proposed to provide a more detailed definition of the genomic features of aggressive cancers such as GBM by mediating O6-methylguanine-DNA methyltransferase (MGMT) and alkylpurine-DNA-N-glycosylase (APNG) which repair DNA damage leading to TMZ resistance." (PMID 39459612, 2024). "Depletion of MGMT led to cancer cell cycle arrest and cell apoptosis." (PMID 39041891, 2024). "Retroviral and lentiviral vectors expressing inhibitor-resistant MGMT mutants have been utilized to protect against the myelosuppressive toxicity of chemotherapy drugs and prevent therapy-related secondary hematopoietic malignancies." (PMID 38254819, 2024). "The intricate interplay between MGMT and these chemotherapeutic agents is of paramount importance for the development of strategies to circumvent resistance and enhance treatment efficacy in the realm of cancer therapy." (PMID 39055560, 2024). "MGMT plays a major role in conferring cancer resistance to alkylating agents." (PMID 38892179, 2024). "Understanding MGMT is crucial for developing precise cancer treatments and advancing patient care." (PMID 39055560, 2024).
cancer (continued). "Likewise, modulation of MGMT expression or activity is expected to be a promising therapeutic target to promote the efficacy of DTIC/TMZ in cancers." (PMID 37024907, 2023). "This indicates that the methylation status of the MGMT promoter might influence CHI3L1's function in human cancers." (PMID 37902124, 2023). "MGMT methylation was detected in 59% in the advanced cancer stage compared to 41% in early stage." (PMID 37510370, 2023). "Hence, the administration of MGMT inhibitors and some alkylating agents enhances the anti-malignant effect of some cancers, which is used as adjuvant therapy in some types of cancer." (PMID 37373325, 2023). "Then, the MGMT inhibitors (such as Lomeguatrib) enhance the death of cancer cells through interference with DNA repair, and this interference on macrophages during sepsis may reduce macrophage hyper-inflammation." (PMID 37373325, 2023). "Despite its lipophilic nature, resistance to TMZ is observed in GBM cells and cancers that express high levels of O6-methylguanine-DNA methyltransferase (MGMT), which is a DNA repair enzyme that plays an important role in promoting chemoresistance to alkylating agents." (PMID 35889829, 2022). "MGMT is a DNA repair enzyme and therefore involved in acquired cancer drug resistance." (PMID 35682901, 2022). "The results show that about one-third of cancers harbor somatic mutations such as BRCA1/2-mutated breast cancer or ovarian cancer and MGMT-methylated glioblastoma, which may give us a hint on the treatment." (PMID 35281059, 2022). "Western blotting analysis of MGMT expression in primary culture cancer cells showed that the inhibitory ability of (Z)-BP on MGMT could result in TMZ re-sensitization." (PMID 35646111, 2022). "The antimicrobial activity was also tested against modifications of the Saccharomyces cerevisiae: the MutL Homolog 1 (MLH1), Slow Growth Suppressor (SGS1), O-6-MethylGuanine-DNA methyltransferase (MGT1), and RADiation sensitive (RAD14), carrying mutations related to different cancer types." (PMID 35284462, 2022). "Though further work is required to draw concrete mechanistic conclusions between replication stress, MMR, and ATR activation, our study provides evidence for the individual roles of MMR proteins in ATR activation upon TMZ treatment in MGMT-promoter methylated cancer cells." (PMID 35388070, 2022). "From a biological perspective, our data are consistent with the growing evidence suggesting that MGMT may be involved in platinum‐induced DNA damage response (DDR) by playing a role in the homologous recombination signaling in cancer cells." (PMID 35621918, 2022). "Hence, the potential of the synergistic effect between the BETi-MGMT-mediated efficacy and cytotoxicity conferred through modulation of other, MGMT-unrelated cancer relevant pathways will be of importance for successful therapy without overt toxicity." (PMID 36513631, 2022). "TMZ may indeed be considered as a ‘targeted chemotherapy’ and even an agnostic investigational option in cancers with MGMT inactivation." (PMID 35621918, 2022). "Therefore, a significant down-regulating MGMT protein in chemical operations victims is expected to be involved in the development of carcinoma." (PMID 35933451, 2022). "Although the action mechanisms remain unclear, several studies have reported that MGMT expression is correlated with CDDP cytotoxicity in cancer cells." (PMID 33397362, 2021). "Therefore, p16, CDH1, and MGMT methylation status can be suggested as a general methylation based panel marker for all cancers in Iranian patients." (PMID 33883026, 2021).
cancer (continued). "A lack of MGMT repair capacity contributes to the genesis and progression of human cancers because it leads to the accumulation of DNA mutations and chromosomal instability." (PMID 33661424, 2021). "Combi-nitrosourea molecule 27, releasing a DNA cross-linking agent and an inhibitor of MGMT, was designed in response to cancer resistance to chloroethylnitrosoureas (CENUs) induced by MGMT, which repairs O6-alkylated guanine and, subsequently, inhibits the formation of dG–dC cross-links." (PMID 33946916, 2021). "On the other hand, it also suggests that O6BG could act beyond MGMT enzymatic repression, and/or that MGMT could control cancer cell metabolism." (PMID 34769368, 2021). "Consistently, decreased expression of MGMT was observed in several kinds of cancer." (PMID 34544433, 2021). "Furthermore, Philip and his colleagues have reported that MGMT is physically involved in BRCA2-containing molecular complexes in cancer cells." (PMID 33397362, 2021). "Studies have demonstrated that MGMT plays an important role in the pathogenesis of cancers and might be a good biomarker candidate for early cancer detection." (PMID 34540891, 2021). "Our report demonstrated that MGMT promoter methylation status could influence a cancer-relevant gene’s function." (PMID 32820151, 2020). "For the cancer group, the percentages are 25% for p16, 16.7% for MGMT, and 18.8% for RASSF1." (PMID 31903158, 2020). "We speculated that cancer cells with low levels of MGMT could be used to study MGMT-independent mechanisms because these cells are initially sensitive to TMZ but then acquire MGMT-independent resistance mechanisms after drug exposure." (PMID 32899791, 2020). "A biomarker of response to earlier alkalyting agents in different types of cancer, i.e., the methylation of the promoter of the gene O6-methylguanine-DNA methyltransferase (MGMT), is being used today also to predict GBM response to temozolomide and indicate survival." (PMID 32478280, 2020). "However, this is an indirect measurement of MGMT levels, with only a modest correlation between MGMT activity and DNA methylation status that limits its predictive ability to identify resistant cancers." (PMID 32075134, 2020). "However, according to the data from National Cancer database (NCDB) indicated that only 4.9% of GBM patients have MGMT promoter methylation." (PMID 33628188, 2020). "Finally, two miRNA sequences, hsa-miR-4261 and hsa-miR-6836-3p, were selected as potential anti-cancer therapeutics for the regulation of the DNA repair protein, MGMT." (PMID 32029822, 2020). "Methylation of MGMT is the most studied DDR gene for chemo-sensitivity in various cancers." (PMID 32974031, 2020). "Our report demonstrated that MGMT promoter methylation status might influence a gene’s function in human cancer." (PMID 32820151, 2020). "Many cancers exhibit alterations in MGMT activity that may be exploited when treating patients with alkylating chemotherapeutic agents, and MGMT activity in normal tissues may predict inter-individual differences in alkylating agent toxicity." (PMID 30811507, 2019). "Cancer patients with a methylated MGMT promoter exhibit prolonged survival in comparison with patients harboring an unmethylated MGMT promoter when treated with alkylating agents such as TMZ, which is currently considered the first-line anticancer agent for GBM." (PMID 31790459, 2019). "MGMT is downregulated by promoter methylation in various types of cancers." (PMID 31225507, 2019). "However, TMZ has a limited activity mainly due to the overexpression in cancer cells of the DNA repair protein O6-methylguanine-DNA methyltransferase (MGMT)." (PMID 30909628, 2019).
cancer (continued). "Importantly, MR30 showed significantly stronger potency than the clinical EGFR inhibitor gefitinib or the equimolar combination of EGFR and MGMT inhibitors (gefitinib + O6-BG) on 5 out of 7 EGFR expressing cancer cell lines (p<0.01)." (PMID 30416678, 2018). "Importantly, the MGMT/RASSF1A/SEPT9 panel detect cancer both in the colon (proximal and distal) and rectum with a sensitivity of 95.7% for colon and 98.0% for rectum." (PMID 29486770, 2018). "Considering the distinct etiopathogenesis or pathogenesis of different kinds of cancers, more studies of large-scale populations of different ethnicities are required for a more scientific elucidation of MGMT rs12917’s functional role in each particular cancer type." (PMID 30232235, 2018). "Thus, inhibition of MGMT activity in tumors has a great interest for cancer researchers because it can significantly improve the anticancer efficacy of such alkylating agents." (PMID 30404161, 2018). "Therefore, evaluation of specific and capable biomarkers intrinsic to cancer hallmarks, like the prognostic role determined by MGMT gene in our study, becomes mandatory subject to its ability to aid in cancer prediction." (PMID 29712977, 2018). "MGMT is another DNA repair gene that is also inactivated in human cancers by promoter methylation." (PMID 30049288, 2018). "MGMT is a DNA repair protein, and its DNA hypermethylation has been reported in human cancers." (PMID 29805743, 2018). "MGMT protect the cell from cancer by removing adducts from the O6 position of guanine." (PMID 28404957, 2017). "There have been precedents of DNA methylation marks and especially those at promoter-specific CGI regions as more powerful parameters than other molecular information for cancer diagnosis and prognosis, among which MGMT hypermethylation for better outcome to TMZ is the most remarkable one." (PMID 29163774, 2017). "This confirms the basic function of MGMT, which carries an alkyl residue (methyl-, ethyl-, n-propil- and others) from O6 position of guanine on its 145th active site which respectively is localized in the nucleus of “cancer” cells." (PMID 29209407, 2017). "This study was an attempt to compare CPUK02 with 5-AZA as DNMT inhibitor agent and evaluate whether it can induce its anti-cancer effects via altering the level of DNMT3b mRNA, MGMT and SFRP2 methylation pattern in HCT 116 cell line." (PMID 28090275, 2017). "The expression of MGMT protein is significantly reduced in MGMT promoter-methylated cancer cells." (PMID 28000777, 2016). "Thus, the level of activity of the MGMT repair system is important in diagnosis, prognosis and treatment of cancer, particularly for patients with brain tumors and melanomas." (PMID 27035132, 2016). "Thus, inactivation of the O6-methylguanine-DNA methyltransferase (MGMT) gene plays an important role in the progression of cancer characterized by the accumulation of genetic changes." (PMID 26862903, 2016). "Only a weak positive association between MGMT methylation and G > A transitions in non-CpG sites was detected for both the entire series of cancers including the rectum (p = 0.07) and proximal cancers (p = 0.035)." (PMID 25638164, 2015). "We also detected a correlation between β-catenin as shown by western blots against the active form of β-catenin dephosphorylated on Ser37 or Thr41 and the downstream effector Axin 2 and MGMT expression in the majority of cancer cell lines derived from these cancers." (PMID 26603103, 2015). "The exome sequencing data was used to estimate the mutation spectrum in cancers with and without MGMT methylation." (PMID 25638164, 2015). "The combination of these advantages and possibilities suggest that using oncolytic adenoviruses to deliver therapeutic shRNA targeting MGMT protein may be a powerful technique for overcoming resistance to TMZ in human cancers." (PMID 25295108, 2014). "Various authors have reported the effects of MGMT inactivation on other cancer-related genes." (PMID 25015560, 2014).
cancer (continued). "Random sampling from tissues is used to detect the MGMT gene promoter methylation status to predict whether cancer patients are resistant to alkylating agents." (PMID 25211033, 2014). "Therefore, it is conceivable to consider MGMT as a potential therapeutic target for the treatment of cancers." (PMID 25460932, 2014). "Many cancers display high expression levels of MGMT responsible for chemo-resistance." (PMID 23873296, 2013). "Thus, in samples containing >5% methylation, the analysis of the MGMT gene appeared to increase the sensitivity for discriminating cancer from normal colorectal tissues or leukocytes." (PMID 24179526, 2013). "MGMT expression was reduced in HP and SSA/TSA, while the normal expression of MGMT was detected in the correlated cancer tissue, suggesting that HP may be transformed into TSA or SSA, followed by carcinogenesis." (PMID 24223631, 2013). "MGMT promoter methylation has been identified in a wide range of human cancers." (PMID 24160898, 2013). "The promoter that was most commonly methylated (in 92% of the examined carcinoma samples) was MGMT." (PMID 23781508, 2013). "Likewise, loss of MGMT expression, another characteristic of PIK3CA-mutated carcinomas, has been reported to be more frequent in tumors with mucinous differentiation compared with tumors without mucinous differentiation." (PMID 23785428, 2013). "The MGMT promoter contains a CpG island that is methylated in many human cancers." (PMID 22547956, 2011). "In MSS cancers, the presence of hMLH1 and MGMT methylation did not correspond to the loss of immunohistochemical expression (not shown), suggesting incomplete methylation of hMLH1." (PMID 21457162, 2011). "KRAS mutation was significantly more prevalent in carcinomas with MGMT methylation (46.3%) than in cases without MGMT methylation (46.3% vs. 28.5%; P = 0.006)." (PMID 21827707, 2011). "Epigenetic silencing of the O6-methylguanine DNA methyltransferase (MGMT) gene, which encodes a DNA repair enzyme, sensitizes cancer cells to alkylating agents, and is associated with significantly longer survival in GBM patients treated by radiotherapy and concomitant and adjuvant temozolomide." (PMID 21156036, 2010). "It has been demonstrated that promoter methylation in sputum increases with cancer risk, increases as the time to lung cancer decreases, and in the case of CDKN2A/p16 and/or MGMT, can be found in sputum up to 3 years before diagnosis of squamous cell lung cancer." (PMID 18947422, 2008). "To investigate further the role of promoter DNA methylation of genes aberrantly hypermethylated in cancer in hESCs, we compared the DNA methylation and expression status of four of the genes identified in the methylation arrays (MGMT and SLC5A8 from Class B-I, and PYCARD and RUNX3 from Class B-II)." (PMID 18820729, 2008). "The MGMT promoter was most frequently methylated (i.e. in 92% of carcinomas)." (PMID 17971771, 2007). "Validation of our MS-MLPA results by Ms-SNuPE analysis, an alternative method to specifically assess methylation of a single CpG dinucleotide, confirmed the presence of MGMT methylation (at position −459 relative to the transcription start site), in 92% of carcinomas." (PMID 17971771, 2007). "In that study, samples for formal assessment of HR related to MGMT WBC methylation were not available; thus, a potential direct association between normal and cancer tissue MGMT epimutations could not be assessed." (PMID 39980037, 2025). "While we do not have any reason to believe that constitutional MGMT methylation may act differently with respect to gender-related risk for the cancer forms investigated, the effect in males has not been formally investigated." (PMID 39980037, 2025). "Despite extensive research into MGMT’s role in DNA repair and chemotherapy resistance, a critical integration of how its genetic polymorphisms and epigenetic modifications collectively influence treatment outcomes across cancer types is lacking." (PMID 40895460, 2025).